HK1 (hexokinase 1)
Diseases named in the same sentence as HK1 in open-access papers (continued):
Sharing a sentence is not in itself a finding about the gene and the disease.
Macular dystrophy (2 papers, 2017 to 2025). Macular dystrophy is a nonspecific term for retinal degeneration, generally confined to the macula, usually presumed of genetic origin. "We also report that this variant can be associated not only RP but also macular dystrophy, thus expanding the HK1-related phenotypic spectrum." (PMID 28765615, 2017). "Due to the significant clinical variability of HK1-associated IRDs, which can manifest as RP, macular dystrophy or cone-rod dystrophy, even among individuals carrying the same variant, the precise contribution of ABCA4 variants remains plausible but challenging to delineate with certainty." (PMID 40269797, 2025).
nasopharyngeal carcinoma (2 papers, 2011 to 2020). A carcinoma arising from the nasopharyngeal epithelium. "The HK1 was isolated from a well-differentiated EBV-negative nasopharyngeal carcinoma." (PMID 21701587, 2011).
non-spherocytic hemolytic anemia (2 papers, 2017 to 2024). "The HK1 deficiency in erythrocytes causes severe non-spherocytic hemolytic anemia." (PMID 38826208, 2024).
periodontitis (2 papers, 2025). An acute or chronic inflammatory process that affects the tissues that surround and support the teeth. "The key mitochondrial dynamics protein Drp1 interacts with hexokinase 1 (HK1) to induce mitochondrial permeability transition pore (mPTP) opening, leading to NLRP3 inflammasome activation and exacerbation of localized inflammation in periodontitis." (PMID 41459510, 2025).
pulmonary diseases (2 papers, 2019 to 2021). "Mitochondrial ROS also activate the NLRP3 inflammasome in multiple pulmonary diseases, consistent with an inflammation model that includes our IL18-pathway and HK1 results, ROS-related proinflammatory responses to lung capillary pressure, and evidence of alveolar epithelial injury/SDB interactions." (PMID 34446064, 2021).
pulmonary hypertension (2 papers, 2022). Increased pressure within the pulmonary circulation due to lung or heart disorder. "Similarly, the expression of both HK1 gene and protein were increased in a pulmonary hypertension model in rats." (PMID 36359890, 2022).
renal fibrosis (2 papers, 2022 to 2026). A final common manifestation of a wide variety of chronic kidney diseases characterized by glomerulosclerosis and tubulointerstitial fibrosis. "RUNX1 subsequently activated HK1 and SLC2A1, which accelerated glycolysis and renal fibrosis of DKD." (PMID 41694585, 2026). "Hexokinase 1 (HK1) and Hexokinase 2 (HK2) are HK isoenzymes that participate in the proximal step of glycolysis, and these have been recently reported to have a significant role in glycolysis, during the development of renal fibrosis." (PMID 34983531, 2022).
retinal detachment (2 papers, 2020 to 2023). An eye emergency condition which may lead to blindness if left untreated. "In contrast, selective deletion of HK2 results in enhanced PR death after retinal detachment despite a compensatory increase in HK1 expression." (PMID 37626853, 2023). "Under acute outer retinal stress induced by experimental retinal detachment, HK2-to-HK1 isoform switching increases rod photoreceptor susceptibility to cell death." (PMID 32499533, 2020). "Interestingly, we observed a similar increase in HK1 enrichment in the mitochondrial fraction following retinal detachment in cKO animals." (PMID 32499533, 2020). "HK1 has been shown to have similar anti-apoptotic activity in non-retinal cells, but an increased expression of HK1 following the deletion of HK2 was unable to compensate for HK2-mediated neuroprotection, leading to increased PR death following retinal detachment." (PMID 37626853, 2023).
retinal dystrophies (2 papers, 2017 to 2024). "Here, by targeted capture sequencing of known IRD-associated genes, we report four additional IRD cases with this variant, further confirming the disease association and supplementing the described phenotypic variability of HK1-related retinal dystrophy." (PMID 28765615, 2017).
squamous cell carcinoma of the lung (2 papers, 2019 to 2023). "Overexpression of Hexokinase 1 blocked the ability of pacritinib to inhibit glucose consumption in squamous cell lung cancer cells." (PMID 36697489, 2023). "This suggests a model in which pacritinib blocks glucose consumption in squamous cell lung cancer cell lines mostly by limiting Hexokinase 1 expression." (PMID 36697489, 2023). "We show that Hexokinase 1 overexpression can rescue the inhibitory effect of pacritinib on glucose consumption, suggesting Hexokinase 1 as a major driver of elevated glucose consumption in squamous cell lung cancer cells and a potential target for additional therapeutic strategies." (PMID 36697489, 2023). "The best studied glucose transporters and hexokinase enzymes in cancer, including in squamous cell lung cancer, are GLUT1, SLC2A3 (also known as Glucose Transporter 3 or GLUT3), Hexokinase 1, and Hexokinase 226,27." (PMID 36697489, 2023). "In conclusion, we identify pacritinib as a strong inhibitor of squamous cell lung cancer glucose consumption that functions by inhibiting FLT3 and limiting Hexokinase 1 expression." (PMID 36697489, 2023).
ulcerative colitis (2 papers, 2013 to 2025). An inflammatory bowel disease involving the mucosal surface of the large intestine and rectum. "Concerning chronic autoimmune/inflammatory diseases in human, a recent publication has suggested that HK-1 may be involved in the pathophysiology of inflammatory bowel diseases, such as ulcerative colitis, but no data are available on its role in arthritic diseases." (PMID 23626716, 2013).
allergic asthma (1 paper, 2019). A asthma with a basis in a pathological type I hypersensitivity reaction. "We showed that HK1 DNAm levels were also strongly associated with atopy and FeNO, which may indicate that the regulation of this gene is particularly important in allergic-asthma." (PMID 31367216, 2019).
Anxiety (1 paper, 2023). Intense feelings of nervousness, tension, or panic often arise in response to interpersonal stresses. "These expression patterns well explain our main functional results demonstrating the role of HK-1 in anxiety and stress regulation, as well as chronic stress-induced pain behavior of the mouse." (PMID 37973885, 2023).
astrocytoma (1 paper, 2010). "In addition, HK-1 has been reported to induce a desensitization of NK1 receptors in human embryonic kidney cells, rabbit jugular veins, U251 MG astrocytoma cells and scratching behavior in rats." (PMID 20929541, 2010).
autosomal dominant retinitis pigmentosa (1 paper, 2017). Autosomal dominant retinitis pigmentosa (RP) is an autosomally dominant inherited retinal dystrophy leading to progressive loss of the photoreceptors and retinal pigment epithelium and resulting in blindness usually after several decades. "In the present study, we identified four unrelated IRD families with the HK1 p.E851K variant, which was previously reported to cause autosomal dominant retinitis pigmentosa (RP), and described their detailed clinical phenotypes." (PMID 28765615, 2017).
cataract (1 paper, 2023). Partial or complete opacity of the crystalline lens of one or both eyes that decreases visual acuity and eventually results in blindness. "The reason why HK1 decreased by 50% was enough to cause cataracts and apoptosis might be that IMM potential and mitochondrial integrity were destroyed in LECs." (PMID 37414399, 2023). "In vivo, experiments should be performed in mice to verify the role of MIR-34A and HK1 in cataracts." (PMID 37414399, 2023). "Therefore, to determine whether MIR34A modulates LEC apoptosis and cataracts through the HK1/caspase 3 signaling pathway, we detected the expression of caspase 3 with or without MIR34A mimics or siHK1." (PMID 37414399, 2023). "Specifically, our results from cultured cells and mouse lenses reveal that MIR34A modulates the HK1/caspase 3 signaling pathway and has a crucial role in LEC apoptosis and cataracts." (PMID 37414399, 2023). "Based on this finding, we focused on the function of MIR34A and HK1 in the progress of cataracts, whereby the human lens epithelial cell line SRA01/04 and mouse lens were treated with MIR34A mimics and HK1 siRNA." (PMID 37414399, 2023). "Many questions remain to be answered in mice, including whether the expression of HK1 is abnormal in the LECs of mice and whether regulating the expression of MIR34A and HK1 can prevent cataracts." (PMID 37414399, 2023). "To evaluate whether Mir34a plays a crucial role in the pathological development of cataracts via regulating the expression of HK1, we cultured the mouse lens in vitro with or without Mir34a mimics, siHk1, or Hk1 inhibitor (deoxyglucose)." (PMID 37414399, 2023).
central precocious puberty (1 paper, 2021). "Our data only identified HK3 without HK1, 2, 4 that suggested HK3 may also play a particular role in central precocious puberty and further explore the distribution of HK3 in central precocious puberty patients’ tissue would be important to clarify its functions." (PMID 34748517, 2021).
chronic kidney disease (1 paper, 2025). Impairment of the renal function secondary to chronic kidney damage persisting for three or more months. "This study investigates the regulatory role of HK1-mediated glycolysis in NLRP3 inflammasome-driven pyroptosis during chronic kidney disease (CKD)-associated vascular calcification (VC) and the protective effects of Irisin/FNDC5." (PMID 41503885, 2025).
chronic lymphocytic leukemia (1 paper, 2019). "CDK7 may promote HIF1α transcriptional activity in chronic lymphocytic leukemia cell lines, and the expression of GLUT1, GLUT3, Hexokinase 1, and Hexokinase 2 is regulated by HIF1α43,44." (PMID 31784510, 2019).
chronic myelocytic leukemia (1 paper, 2023). "High expression of PTEN was able to promote protein kinase B (PKB/AKT) activity while inhibit hexokinase 1 (HK1) ubiquitination, thereby stimulating tumorigenesis of chronic myelocytic leukemia (CML) cells." (PMID 37365581, 2023).
cognitive decline (1 paper, 2025). "HK1, regulating glucose metabolism for neuronal energy, is crucial since impaired glucose metabolism is a feature of AD; HK1 dysregulation intensifies bioenergetic deficits and contributes to cognitive decline." (PMID 40430038, 2025).
Cognitive impairment (1 paper, 2022). Abnormal cognition is characterized by deficits in thinking, reasoning, or remembering. "Moreover, oligodendrocyte glycolytic deficiency through the dynamin-related protein 1- hexokinase 1- NLR family pyrin domain containing 3 signaling axis contributes to white matter degeneration and cognitive impairment in AD." (PMID 36353631, 2022).
colitis (1 paper, 2024). Inflammation of the colon. "Specifically, our results revealed decreased levels of glycolytic enzymes, including HK1, GPI, PFKL, ALDOA, and ALDOB in colitis." (PMID 38668322, 2024). "We observed a reduced relevant abundance for hexokinase (HK1), glucose-6-phosphateisomerase (GPI), phosphofructokinase (PFKL), fructose 1,6-biphosphate aldolase enzymes (ALDOA, ALDOB), triosephosphate isomerase (TPI), phosphoglycerate kinase 1 (PGK1), and alpha enolase (ENO1) in colitis." (PMID 38668322, 2024).
dyslipidaemia (1 paper, 2011). "Based on the present results, we suggest that the T-allele of rs7072268 in HK1 associates with T2DM as well as fasting dyslipidaemia in non-diabetic individuals prior to Bonferroni correction." (PMID 21781351, 2011).
esophageal squamous cell carcinoma (1 paper, 2020). Esophageal squamous cell carcinoma (ESCC) is a type of esophageal carcinoma (EC) that can affect any part of the esophagus, but is usually located in the upper or middle third. "Although most studies focused on HK2, some studies found that the expression of HK1 is connected with disease progression, invasion, and poor survival in patients with esophageal squamous cell carcinoma." (PMID 33029143, 2020).
fibrosis (1 paper, 2022). the formation of excess fibrous connective tissue in an organ or tissue in a reparative or reactive process. "However, Csn-B barely inhibited lEV HK1 release from active HSCs, implying that it acts through a different mechanism dependent on cell type and tissue specificity in fibrosis." (PMID 36192599, 2022).
gastric tumor (1 paper, 2023). "GO-Y022 treatment enhanced Hk1 expression in gastric tumor cells, thus promoting glycolysis, proliferation, and lymphatic metastasis." (PMID 36814928, 2023). "The high Hk1 expression in gastric tumors showed poor prognosis." (PMID 36814928, 2023).
gastrointestinal stromal tumour (1 paper, 2010). "Gastrointestinal stromal tumour implantation in nude mice resulted in local and systemic hK1 expression proportional to tumour dimension." (PMID 20859288, 2010). "Here, we investigate the expression and functional relevance of hK1 in human gastrointestinal stromal tumour (GIST)." (PMID 20859288, 2010).
Gilbert syndrome (1 paper, 2024). An autosomal recessive inherited disorder characterized by unconjugated hyperbilirubinemia, resulting in harmless intermittent jaundice. "We now report a novel pathogenic sense variant in exon 7 of the HK1 gene in a patient with coexistent Gilbert syndrome." (PMID 39766843, 2024).
Hypertension (1 paper, 2015). The presence of chronic increased pressure in the systemic arterial system. "CAD severity and hypertension werenot observed to significantly affect urinary hK1-specific amidase activity." (PMID 26351984, 2015).
insulinomas (1 paper, 2022). "The HK1 expression in clusters cultured in stromal medium that was about double that of those in differentiation medium as well as the presence of glucagon in clusters substantiates, at minimum, a lower potential for insulinoma formation." (PMID 35769100, 2022). "In contrast to normal feline β cells, insulinoma cells express the HK1 gene and do not show glucagon protein expression, similar to lacking glucagon protein expression within Men1-ablated murine insulinomas." (PMID 35769100, 2022).
Intellectual disability (1 paper, 2025). "The female patient SRP1400-II:1 was diagnosed with RP along with intellectual disability, associated with a de novo heterozygous likely pathogenic missense variant in the HK1 gene (c.1334 C > T, p.(Ser445Leu))." (PMID 40269797, 2025).
laryngeal carcinoma (1 paper, 2023). Carcinoma that arises from the laryngeal epithelium. "By constructing ZBTB10-sgRNA and knocking out ZBTB10 in Hep2 cells, we found that, after the knockout, both the mRNA and protein levels of HK1 were decreased in laryngeal cancer Hep2 cells." (PMID 37834257, 2023). "In our study, differentially expressed genes in the Hep2 laryngeal cancer cells treated with M2 macrophage supernatant were identified by RNA-seq analysis, and the expression of the glycolysis-related gene hexokinase HK1 was significantly increased." (PMID 37834257, 2023). "We performed immunohistochemical staining of a tissue microarray containing 80 samples of human laryngeal cancer tissue to determine the expression patterns of HK1 and ZBTB10." (PMID 37834257, 2023). "In this study, we aimed to explore the effect of TAM on laryngeal cancer with OSA, and investigated the role of HK1 in TAM-inducing glycolysis of laryngeal cancer cells when exposed to IH conditions." (PMID 37834257, 2023). "The hexokinase inhibitor 2-deoxy-D-glucose and HK1 shRNA were applied to verify this finding, confirming that M2-like TAMs enhanced glycolysis in laryngeal cancer cells through HK1 under intermittent hypoxic conditions." (PMID 37834257, 2023). "IH promotes TAM-induced glycolysis in laryngeal cancer cells via regulation of HK1 expression through activation of CLEC3B and ZBTB10." (PMID 37834257, 2023). "We found that HK1 was highly expressed in laryngeal cancer tissues and was predominantly localized in the cytoplasm." (PMID 37834257, 2023). "Through analysis of genes related to glycolysis, we found that, in laryngeal cancer cells exposed to M2 macrophage culture supernatant, hexokinase (HK1) expression was elevated." (PMID 37834257, 2023). "We next confirmed that the expression trend was consistent between ZBTB10 and HK1 in human laryngeal cancer tissues." (PMID 37834257, 2023). "The same result was found in laryngeal cancer Hep2 cells with transient overexpression or knockout of HK1." (PMID 37834257, 2023). "Knockdown of ZBTB10 decreased HK1 expression, and overexpression of ZBTB10 increased HK1 expression in both laryngeal cancer cells and 293T cells." (PMID 37834257, 2023). "In our research, we also found that OSA-related IH-induced TAMs promoted glycolysis in laryngeal cancer cells through HK1." (PMID 37834257, 2023). "In addition, Pearson correlation analysis showed that the HK1 expression level was positively correlated with the ZBTB10 expression level in the laryngeal cancer tissue microarray (R2 = 0.3157; p < 0.0001)." (PMID 37834257, 2023). "In addition, we constructed HK1-shRNA, which specifically inhibited HK1, and found that silencing HK1 inhibited the proliferation and migration of Hep2 laryngeal cancer cells." (PMID 37834257, 2023). "Comprehensive RNA-seq analysis disclosed a marked elevation in the expression levels of the transcription factor ZBTB10, while evaluation of a laryngeal cancer patient tissue microarray demonstrated a positive correlation between ZBTB10 and HK1 expression in laryngeal carcinoma." (PMID 37834257, 2023). "As ZBTB10-mediated regulation of HK1 affects glycolysis in laryngeal cancer, our findings may provide new potential therapeutic targets for laryngeal cancer." (PMID 37834257, 2023). "Hence, our results confirmed that ZBTB10 binds to a candidate sequence in the promoter of HK1 and transcriptionally regulates HK1 gene expression, increasing glycolysis and affecting malignant phenotypes in laryngeal cancer cells." (PMID 37834257, 2023). "Additionally, we demonstrate that HK1 is transcriptionally regulated by ZBTB10, indicating that targeting ZBTB10 or HK1 may be a potential approach for treating laryngeal cancer patients with OSA." (PMID 37834257, 2023).
liver cirrhosis (1 paper, 2022). "In clinical samples, the levels of HK1 were much higher in plasma lEVs isolated from patients with liver cirrhosis than those from healthy donors." (PMID 36192599, 2022).
liver disease (1 paper, 2018). "Interestingly, there is emerging evidence suggesting that anti-HK1 may be a marker of poor prognosis in PBC patients, with increased risk in liver disease progression and lower transplant free survival." (PMID 29554146, 2018).
male infertility (1 paper, 2020). The inability of the male to effect fertilization of an ovum after a specified period of unprotected intercourse. "Decreased phospho-tyrosine signals at 100 kDa suggest a lack of hexokinase-1 activity, which is associated with male infertility." (PMID 32466766, 2020).
metastatic colorectal cancer (1 paper, 2020). "In a previous study in metastatic colorectal cancer, we found mRNA tumor overexpression of GLUT-1 and the glycolytic genes hexokinase 1 (HK-1) and 2 (HK-2), pyruvate kinase isoform 2 (PKM-2) and lactate dehydrogenase isoform A (LDH-A)." (PMID 32372141, 2020).
metastatic tumors (1 paper, 2023). "To understand the detailed changes in the cellular system between primary tumors and metastatic tumors, we conducted H&E staining, immunofluorescence staining of Ki-67, and Western blotting of Glut1, HK1, HK2, PKM2, and PC." (PMID 36677035, 2023).
migraine (1 paper, 2022). "We detected three energy metabolism-related enzymes (PKM, G6PD, and HK1) among the DEPs in the healthy controls and patients with migraine." (PMID 36248663, 2022).
Miscarriage (1 paper, 2019). A pregnancy that ends at a stage in which the fetus is incapable of surviving on its own, defined as the spontaneous loss of a fetus before the 22th week of pregnancy. "Since glucose metabolism is very important in embryonic development, the downregulation expression of the HK1 might induce miscarriage." (PMID 31288842, 2019).